CTTN (cortactin)
Diseases named in the same sentence as CTTN in open-access papers (continued):
Sharing a sentence is not in itself a finding about the gene and the disease.
ischemic stroke (1 paper, 2024). A stroke disorder caused by obstruction of blood flow to the brain, due to thrombotic (local blood clot formation) or embolic (due to a blood clot or other material traveling from another site) event. "Likewise, dysregulation of other actin-related proteins, such as cortactin, has been shown to play an essential role in mediating ischemic stroke injury by preserving mitochondrial stability and survival in astrocyte cells." (PMID 38256947, 2024).
meningococcal infection (1 paper, 2012). Infections with bacteria of the species neisseria meningitidis. "In addition, meningococcal infection leads to cortactin phosphorylation." (PMID 22768099, 2012).
metastatic melanoma (1 paper, 2021). A melanoma that has spread from its primary site to another anatomic site. "Also, amplifications in loci 1p12 (NOTCH2), 3p13 (MITF), 13q13.3 (FGF3/4, CTTN) and 22q13 (MLK1) were found in both cytolytic subtypes of metastatic melanoma." (PMID 33779796, 2021).
myocardial infarction (1 paper, 2014). Gross necrosis of the myocardium, as a result of interruption of the blood supply to the area, as in coronary thrombosis. "In conclusion, the subcellular structural remodeling of Kv1.5, SAP97 and cortactin maintained and normalized the function of the Kv1.5 channel in Purkinje cells that survived myocardial infarction." (PMID 25184222, 2014).
nasal polyps (1 paper, 2022). "The expression of CTTN was also reported to be higher in nasal polyps of females when compared to males, suggesting a possible explanation for differences in AERS severity." (PMID 35562995, 2022). "CTTN expression was assessed in nasal polyps from AERS patients by immunohistochemistry." (PMID 35562995, 2022).
neuroblastoma (1 paper, 2026). Neuroblastoma (NB) is the most common solid, extracranial childhood tumor. "We verified that DANCR overexpression in neuroblastoma cells significantly enhances the interaction of ABL2 with cortactin, which also affects SSH1-cofilin activity and stabilizes F-actin networks." (PMID 41602364, 2026).
neutropenia (1 paper, 2022). A decrease in the number of neutrophils found in the blood. "Thus, cortactin deficiency prevents neutropenia in septic mice." (PMID 35625756, 2022). "Our observation that neutropenia is prevented in septic cortactin-KO mice is likely the consequence of defective neutrophil transmigration and ensures an effective intravascular immune response to better control systemic infection." (PMID 35625756, 2022).
Obesity (1 paper, 2019). Accumulation of substantial excess body fat. "CTTN’s protein product Cortactin binds to and is indirectly phosphorylated by obesity factor PTP1B." (PMID 31296617, 2019).
ovarian tumors (1 paper, 2015). "The current study highlights the involvement of the ‘V0a2’ isoform of V-ATPase on the surface of metastatic ovarian tumors and its co-association with cortactin, a component of invasion machinery at the advancing edge of the tumor cell surface." (PMID 25686833, 2015).
pemphigus (1 paper, 2019). Pemphigus is a group of rare autoimmune diseases that cause blistering of the skin and mucous membranes (mouth, nose, throat, eyes, and genitals).This conditioncan occur at any age, but often strikes people in middle or older age. "Since the pathogenesis of pemphigus appears to be complex and to include direct inhibition of Dsg3 binding as well as signaling events, the question arises about the role of Src and cortactin for loss of cell cohesion when compared to other mechanisms." (PMID 31024527, 2019). "Taken together, we show that Src contributes to loss of cell adhesion primarily downstream of antibodies against Dsg3 in pemphigus by mechanisms which are both cortactin-dependent and –independent." (PMID 31024527, 2019). "In the work presented here, we show for the first time that cortactin regulates reconstitution of cell adhesion in pemphigus and provide new insights into the role and function of Src in PV." (PMID 31024527, 2019).
periodontitis (1 paper, 2025). An acute or chronic inflammatory process that affects the tissues that surround and support the teeth. "BNIP3L and CTTN were downregulated in periodontitis, correlating negatively with disease prevalence, immune infiltration, and inflammatory pathways, whereas VPS13C and MAP1LC3B were upregulated, showing positive correlations." (PMID 40859550, 2025).
Peritoneal Fibrosis (1 paper, 2023). Disorder characterized by a wide range of structural changes in PERITONEUM, resulting from fibrogenic or inflammatory processes. "Since cortactin is only expressed in the cytoplasm of cells, we hypothesized that HDAC8 regulated peritoneal fibrosis by participating in cytoplasmic protein regulation." (PMID 36911746, 2023).
renal carcinoma (1 paper, 2014). A carcinoma arising from the epithelium of the renal parenchyma or the renal pelvis. "The studies of breast, head/neck squamous cell cancer, and renal cancers have shown that increased cortactin expression resulted from gene amplification of chromosome 11q13." (PMID 24465712, 2014).
sarcoma (1 paper, 2013). A usually aggressive malignant neoplasm of the soft tissue or bone. "A recent study revealed that AFAP1L1 interacted with the SH3 domain of cortactin, an F-actin-binding protein Although we had previously reported that AFAP1L1 was associated with the progression of sarcomas, how it functions in the invasiveness of tumor cells remains ill defined." (PMID 23326307, 2013).
schizophrenia (1 paper, 2021). A major psychotic disorder characterized by abnormalities in the perception or expression of reality. "ARP2/3 transcript levels are reduced in the prefrontal cortex in the post-mortem brain in schizophrenia, as are nucleation promotion factors that regulated ARP2/3 (cortactin, N-WASP) and are suggested to contribute to dendritic spine loss in that region." (PMID 34502103, 2021).
Splenomegaly (1 paper, 2019). Abnormal increased size of the spleen. "However, cortactin overexpression was not related to sex, risk, immunophenotype, infections, cytopenia, hepatomegaly, or splenomegaly." (PMID 30573781, 2019).
steatosis (1 paper, 2022). Increased lipid within the cytoplasm of cells. "In particular, the up-regulation of GTPase HRAS is associated with carcinoma, while up-regulation of Cortactin and down-regulation of YKT6 and DFFA are related to tumor cell invasiveness and down-regulation of PPIF/CypD may lead to steatosis." (PMID 36016316, 2022).
teratoma (1 paper, 2018). A non-seminomatous germ cell tumor characterized by the presence of various tissues which correspond to the different germinal layers (endoderm, mesoderm, and ectoderm). "Interestingly, Hakai-MDCK xenograft tumours show Cortactin expression only in the cytoplasm, whereas in MDCK teratoma is also highly enriched in the nucleus." (PMID 29472634, 2018).
thyroid tumor (1 paper, 2016). A benign or malignant neoplasm affecting the thyroid gland. "CTTN expression was also increased in additional DTC specimens, with a significant induction in CTTN protein evident in thyroid tumors (>2.5-fold induction)." (PMID 27603901, 2016). "CTTN expression has not been determined before in human thyroid tumors." (PMID 27603901, 2016).
tongue cancer (1 paper, 2018). A malignant neoplasm affecting the tongue. "ERK contributes to tongue cancer development by increasing both cancer cell proliferation and migration via cortactin activation." (PMID 30344309, 2018). "A new experimental system involving 3D culture using the Cellbed, which accurately mimics the morphology of tumour cells in vivo, suggested that p-ERK activates cortactin and contributes to the formation of invadopodia in tongue cancer cells and tumour development." (PMID 30344309, 2018). "In summary, our results suggest that cortactin is activated by p-ERK and contributes to invadopodia formation and tongue cancer development based on experiments performed in a novel 3D culture system using Cellbed." (PMID 30344309, 2018). "Morphological changes in 3D-cultured tongue cancer cells (HSC-3 and HSC-4) following the administration of ERK inhibitor (FR180204) were evaluated by immunofluorescence staining, particularly to determine the sites of F-actin and cortactin colocalization." (PMID 30344309, 2018).
Wiskott-Aldrich syndrome (1 paper, 2020). Wiskott-Aldrich syndrome (WAS) is a primary immunodeficiency disease characterized by microthrombocytopenia, eczema, infections and an increased risk for autoimmune manifestations and malignancies. "DCs express multiple activators of Arp2/3 complex, of which two have been implicated in maturation-associated changes in actin architecture: Hematopoietic lineage cell-specific protein 1 (HS1), the hematopoietic homolog of cortactin, and WASp, the protein defective in Wiskott-Aldrich syndrome." (PMID 32720892, 2020).
cancer (185 papers, 2005 to 2026). A tumor composed of atypical neoplastic, often pleomorphic cells that invade other tissues. "The CTTN-encoded protein cortactin promotes actin polymerization, which enhances cancer cell migration and invasion." (PMID 41286896, 2025). "In Matrigel-coated Boyden chamber assays, enhanced migration and invasion of cancer cells transformed with PIK3CA mutations were shown to depend on AKT1-mediated phosphorylation of cortactin." (PMID 38786098, 2024). "Cortactin plays a key role in regulating cell migration and invasion, processes that are closely associated with cancer progression." (PMID 37761244, 2023). "The cortactin locus, encoded by the cortactin gene within chromosome region 11q13, is amplified in several human cancers." (PMID 37761244, 2023). "The nucleation-promoting factor (NPF) and actin-associated protein cortactin localize to invadopodia in invasive cancer cells, where cortactin regulates their formation and function." (PMID 34440806, 2021). "Cortactin over-expression is common to several cancer types, and is associated with enhanced motility, invasion and invadopodia activity." (PMID 34088320, 2021). "Cortactin is a key regulator of invadopodia assembly and function in cancer cells, and amplification of cortactin is linked to an increase in metastasis of carcinoma." (PMID 32678085, 2020). "Our finding also indicates that Cortactin is downstream of Wnt signaling, and associated to other cancer type s." (PMID 32033570, 2020). "In various cancers, cortactin overexpression is associated with a dismal prognosis and increased metastasis." (PMID 30976201, 2019). "Fixed cells were stained to visualize DNA (blue), cytoskeleton (F-actin, red) and the actin-associated protein cortactin (green), constituting the marker of invadopodia-adhesive structures with proteolytic activity, involved in cancer cell invasion." (PMID 31877948, 2019). "CTTN phosphorylation is required for actin regulation and is responsible for lamellipodia formation and associated with enhanced cancer cell migration." (PMID 31108958, 2019). "During the invasion process, CTTN plays an essential role in invadopodia, actin-rich subcellular protrusions associated with degradation of the extracellular matrix by cancer cells." (PMID 30220969, 2018). "At sub-lethal doses, treatment of HER2+ cancer cells with Myc B resulted in rapid loss of leading edge protrusions and formation of aggresomes containing F-actin and the actin regulatory protein Cortactin." (PMID 30467396, 2018). "Accordingly, the CTTN gene encoding for Cortactin is located in the 11q13 region, a chromosomal region that is frequently amplified in malignant tumors." (PMID 26345720, 2015). "Sub-cellular distribution of V-ATPase-V0a2 confirmed its localization on plasma-membrane, where it was also co-associated with cortactin, an F-actin stabilizing protein at leading edges of cancer cells." (PMID 25686833, 2015). "Overexpression of cortactin is associated with high invasiveness of hepatoma carcinoma cells, which closely involved poor human HCCs prognosis that caused by cancer embolus and metastasis." (PMID 23518204, 2013). "Overexpression of cortactin is closely associated with poor human HCCs prognosis that caused by cancer embolus and metastasis." (PMID 23518204, 2013). "As our data showed, cortactin immunohistochemistry score was significantly associated with cancer embolus in portal vein and distant neoplasm metastasis, by both separately analysis and jointly analysis." (PMID 23518204, 2013). "Invadopodia formation is the major manner of cancer invasion and is associated with many proteins, including F-atin and cortactin that are considered as reliable indicators for cancer invasion." (PMID 23441195, 2013). "Interactions between FAK and cortactin downstream of β1 integrin have been linked to cancer cell resistance to radiotherapy." (PMID 22952866, 2012).
cancer (continued). "The actin-binding protein cortactin is commonly upregulated in multiple cancer types and is associated with increased cell migration." (PMID 21079800, 2010). "In addition, the cytoplasmic protein tyrosine kinase Syk associates with CTTN and promotes integrin-mediated phosphorylation on tyrosine, which correlates with the inhibition of cell motility in cancer cells." (PMID 35562995, 2022). "Cortactin overexpression is associated with increased metastasis formation and worse outcome in different types of solid tumors, thus highlighting a critical role of cortactin in cancer progression." (PMID 33773540, 2021). "Copy number amplifications are frequently observed in the chromosomal region 11q13, which harbors besides ANO1, genes CCND1, ORAOV1, PPFIA1, FADD and CTTN, the expression of which is associated with cancer proliferation, migration, apoptosis or poorer prognosis." (PMID 33803266, 2021). "Cortactin has been demonstrated to be associated with cancer." (PMID 29152154, 2017). "Many other studies suggest that cortactin promotes cell motility and invasion, including a critical role in invadopodia, actin rich-subcellular protrusions associated with degradation of the extracellular matrix by cancer cells." (PMID 29221118, 2017). "Thus, besides supporting the association of CORTACTIN and neutrophils with increased metastasis in cancer patients, these findings unravel a novel mechanism of neutrophil-mediated tumor migration and progression." (PMID 23423155, 2013). "Consistent with its role in cellular migration and invasion, high CORTACTIN expression and/or activation has been found to associate with increased metastasis and poor clinical outcome in several types of cancer, such as renal carcinoma, gastric cancer, colorectal adenocarcinoma, or melanoma." (PMID 23423155, 2013). "Among these candidates, CTTN, a gene related to tumor cell invasion and migration, for which the encoding protein is named cortactin, may be a potential molecular marker that can predict prognosis of cancer patients." (PMID 23518204, 2013). "Cortactin overexpression was associated with significantly increased local recurrence rates (49 vs 28% for high and low expressing carcinomas, respectively), decreased disease-free survival (17 vs 61%), and decreased the 5-year overall survival of (21 vs 58%), independently of the EGFR status." (PMID 18268492, 2008). "Moreover, previous studies reported that protein expression of cortactin could be associated with advanced histologic grades and poor differentiation in the cancers of colon, pancreas, and lung." (PMID 33407452, 2021). "In addition, the gene encoding cortactin is amplified in various human cancers." (PMID 34439396, 2021). "Therefore, dysregulation of CTTN causes many diseases, especially cancer." (PMID 32120844, 2020). "Lysine acetylation within the tandem repeat region of cortactin (CTTN) regulates its actin-binding function and has been linked to cancer cell migration and neuronal development." (PMID 41640095, 2026). "These observationswere confirmed by the overexpression of cortactin, a marker relatedto cancer cell invasion and invadopodia formation." (PMID 41368899, 2026). "As one of the cytoskeletal proteins for invasive cell assembly in cancer cells, cortactin regulates the remodeling of the actin cytoskeleton by activating the Arp2/3 complex." (PMID 41158752, 2026). "Phosphorylation of cortactin, particularly its tyrosine phosphorylation by Src, is strongly correlated with increased cortactin-induced ruffling activity and enhanced migration and invasiveness of cancer cells." (PMID 40328105, 2025). "Drp1 and cortactin play significant roles in malignant transformation and LN metastasis, highlighting their potential role as cancer biomarkers." (PMID 40217339, 2025). "Cortactin, a member of actin-binding protein family, plays an important role in cancer cell migration, cytoskeleton remodeling, and Epithelial–Mesenchymal Transition (EMT)." (PMID 40282339, 2025).